PML (PML nuclear body scaffold)
Diseases named in the same sentence as PML in open-access papers (continued):
Sharing a sentence is not in itself a finding about the gene and the disease.
leukemia (continued). "While in leukemia cells with AML1-ETO and PML-RARa fusion proteins inhibition of PARP leads to an accumulation of DNA damage that results in cell differentiation and cell death, leukemia cells expressing MLL fusion proteins exhibit resistance to inhibition of PARP." (PMID 34594227, 2021). "Indeed, in APL leukemia cells, ATO acts mainly on the degradation of the PML-RARα fusion protein, thus explaining the anti-leukemia therapeutic effect by ATO." (PMID 29467594, 2018). "To establish a standardized method without interlaboratory discrepancies, we developed a novel one-step reverse transcription quantitative PCR (RT-qPCR) assay, called “the Eprobe leukemia assay,” for major and minor BCR-ABL1, RUNX1-RUNX1T1, and various isoforms of PML-RARA." (PMID 30281597, 2018). "The precise leukemogenic mechanism of the PML/RARA oncoprotein has not been fully elucidated, and its presence in transgenic mice is not per se sufficient to cause leukemia, but leads to a myeloproliferative syndrome." (PMID 27626703, 2016). "In summary, these data show that the AAFPs PML/RARα and DEK/NUP214 initiate leukemia by transforming a small subpopulation of LT-HSCs, but both maintain already established leukemia from already committed cell populations in the BM suggesting a difference between L-ICs and L-MCs." (PMID 25568664, 2014). "Moreover, treatment of APL cells with therapeutic doses of all-trans retinoic acid (ATRA) induces transcriptional activation by PML-RARα, followed by PML-RARα degradation and rapid and effective APL blast differentiation and leukemia de-bulking." (PMID 24711541, 2014). "Because ATRA possesses a strong capacity to activate wild-type RAR-α and its downstream targets, ATRA promotes granulocytic differentiation in other leukemia cells, even those lacking a PML-RAR-α fusion protein." (PMID 23460888, 2013). "Aberrant H3.3 deposition may also play a role in leukemia pathogenesis, given DAXX role in PML-RARα-driven transformation and the identification of a DAXX missense mutation in acute myeloid leukemia." (PMID 23760585, 2013). "Ectopic expression of PML/RARα and PLZF/RARα in hematopoietic cells mimics the leukemic phenotype by inducing a differentiation block and an aberrantly activated self-renewal capability, leading to the development of leukemia in mice." (PMID 23152790, 2012). "PML::RARα fusion oncoprotein impairs the formation of functional PML nuclear bodies, acts as a transcriptional repressor antagonizing myeloid differentiation, alters DNA repair and oxidoreductive state of the cell, promotes self-renewal of APL initiating cells and leukemia progression." (PMID 40931045, 2025). "In a variety of carcinomas, lymphomas and leukemias, ubiquitination regulates the tumor-suppressive functions of the promyelocytic leukemia protein (PML), but PML-specific DUBs, DUB-controlled PML ubiquitin sites and the functional consequences of PML (de)ubiquitination remain unclear." (PMID 38467608, 2024). "Can PML targeting improve therapy response in non-APL leukemia?" (PMID 37382966, 2023). "In contrast to T618L mutations, truncating mutations are not leukemia initiating in murine models but accelerate leukemia development in the presence of PML‐RARA translocation, suggesting that they may be secondary events." (PMID 35898175, 2022). "Therefore, we further tested this hypothesis in two human leukemia cell lines: HL-60 (M2, C-Myc amplification) cells 38 and NB4 (M3, PML-RARa+) cells." (PMID 34093860, 2021). "Furthermore, FLT3-ITD could cooperate strongly in leukemia induction with a variety of leukemia-initiating gene fusions such as AML1-ETO, MLL-AF9, or PML-RAR α." (PMID 25879624, 2015). "Accordingly, we investigated whether tenovin-6 induces granulocytic differentiation in leukemia cells lacking PML-RAR-α." (PMID 23460888, 2013).
leukemia (continued). "We further defined a critical role for PML in the maintenance of leukemia-initiating cells (LICs) in disease models of chronic myeloid leukemia (CML), and presented a new therapeutic approach based on targeting quiescent LICs by pharmacological inhibition of PML." (PMID 23504288, 2013). "Notably, the cooperative ability of ATO and ATRA to eliminate TICs in TNBC by targeting Pin1 is consistent with the previous findings that genetic or chemical inhibition of Pin1 induces PML/RARα degradation to eradicate leukemia stem cells and treat APL without inducing myeloid differentiation." (PMID 30093655, 2018). "No study has assessed whether the higher frequency of PML-RARA bcr1, involving the PML intron 6 in both de novo and t-APL, or the hotspots on intron 6 identified in t-APL, result from intrinsic sequence-specific properties per se, or from some selected random events that lead to leukemia." (PMID 26053431, 2015). "Moreover, unsupervised hierarchical clustering based on HOX expression divided the leukemias into five main clusters characterized by the presence or absence of prevalent gene rearrangements, i.e., PML-RARa, RUNX1-RUNX1T1(AML1-ETO), CBFb-MYH11 and MLL alterations." (PMID 25539595, 2014). "Post-treatment bone marrow displayed no residual leukemia by flow cytometry; however, FISH for PML/RARA still displayed a high percentage of the same atypical signal pattern." (PMID 39596602, 2024). "While the consequences of these PML/TET2 enforced epigenetic changes were not explored, one should note that in APL, two master genes involved in leukemia initiation or progression (DNMT3A and WT1) regulate the status of 5-methylcytosine, similar to TET2." (PMID 37382966, 2023). "Although ATRA is highly efficient for leukemia harboring PML-RARα gene fusions, ATRA does not show differentiation responses in non-APL leukemia." (PMID 31727951, 2019). "The sequencing results of PML-RARA chRNA qPCR amplifications revealed another fusion transcript joining PML exon 3 and RARA exon 10 present in OM110223 leukemia cells, without corresponding spanning junction read." (PMID 29623188, 2017). "PML/RARα transgenic murine APL models mimic this notion well, in which PML/RARα only does not induce leukemia (PML/RARα transgenic preleukemic mice) and additional secondary events cooperating with PML/RARα promote APL development (PML/RARα transgenic APL mice)." (PMID 33298855, 2020). "The hypothesis that TRIB1 and PML/RARA cooperate has been tested and, while they do not cooperate to drive a shorter latency leukemia in vivo, TRIB1 and PML/RARA have functionally redundant inhibitory effects on C/EBPα, which also impacts responses to therapeutic All-Trans Retinoic Acid (ATRA)." (PMID 27908682, 2017). "Notably, the combination of ATRA with the CDK4/6 inhibitor (CDK4/6i) palbociclib induces enlarged PML-NB-dependent cytotoxicity through conflicting cell cycle signals, driven by ATRA-dependent activation of mitogenic ERK signaling under conditions of cell cycle arrest in non-APL leukemia." (PMID 40753178, 2025).
acute myeloid leukemia (128 papers, 2006 to 2026). Acute myeloid leukemia (AML) is a group of neoplasms arising from precursor cells committed to the myeloid cell-line differentiation. "In one case, whole-genome sequencing of a 39-year-old woman with acute myeloid leukemia (AML) revealed a novel insertional translocation on chromosome 17 that resulted in a pathogenic bcr3 PML-RARA fusion gene." (PMID 24213133, 2011). "Moreover, genes targeted by both PU.1 and PML/RARα were significantly involved in categories associated with oncogenesis, hematopoiesis and the pathogenesis of acute myeloid leukemia." (PMID 23547873, 2013). "In analogy to prostate cancer, truncal point mutations in DNMT3A and gene fusions in PML-RARA are mutually exclusive drivers in acute myeloid leukemia (AML)." (PMID 33531470, 2021). "We previously found that PIR mRNA expression is silenced by the acute myeloid leukemia (AML)-associated fusion proteins PML/RARα and AML1/ETO both in cellular models and in primary blasts form AML patients." (PMID 20089166, 2010). "Recently, it was evaluated in relation to acute myeloid leukemia (AML) that carries the PML–SYK fusion." (PMID 41226319, 2025). "The typical genomic feature of acute myeloid leukemia (AML) M3 subtype is the fusion event of PML/RARα, and ATRA/ATO-based combination therapy is current standard treatment regimen for M3 subtype." (PMID 38322990, 2024). "APL, an M3 variant of acute myeloid leukemia (AML), expresses a fusion oncogene (a fusion of PML gene with RARα gene), leading to translation of the PML/RARα chimeric protein, which blocks hematopoietic progenitor cell differentiation and ultimately leads to APL." (PMID 39253293, 2024). "A key role of 5‐LO for the maintenance of leukemic stem cells was also shown in a PML/RARα‐positive stem cell model of acute myeloid leukemia." (PMID 33205517, 2021). "Overall, degron loss contributes to many of the most highly recurrent gene fusions specific to particular cancer types, including PML-RARA in acute myeloid leukemia (LAML), EGFR-SEPT14 in gliomas, and TMPRSS2-ERG in prostate cancers." (PMID 34795215, 2021). "For example, the relatively well‐studied EML‐ALK fusion in non‐small‐cell lung cancer or the PML‐RAR fusion in acute myelogenous leukemia is found in only 2–5% or 6–10% of these malignancies, respectively." (PMID 30548174, 2019). "It is worth mentioning here that even the relatively well‐studied EML‐ALK fusion in non‐small cell lung cancer or PML‐RAR fusion in acute myelogenous leukemia is only found in 2–5% or 6–10% of these cancers, respectively." (PMID 30548174, 2019). "APL is a subtype of acute myeloid leukemia (AML) that is genetically characterized by a specific chromosomal translocation that yields the promyelotic leukemia/retinoic acid receptor alpha (PML/RARA) fusion gene—a DNA-binding transcription factor." (PMID 29206204, 2017). "Analysis also revealed an association with a pathway category deposited as “Acute Myeloid Leukemia”, which refers to ERK, PI3K and JAK-STAT signaling and transcription regulation pathways including mutated RUNX1 and the fusion genes AML1-ETO, PML-RARA and PLZF-RARA." (PMID 34502231, 2021). "For example, the three genes GRB2, FLT3, and PML, which were found in the acute myeloid leukemia (AML) signaling network, were considered key drug target genes." (PMID 34238960, 2021). "Another gene fusion that is effectively treatable is the PML-RARA fusion in acute myeloid leukemia (AML)." (PMID 32727569, 2020). "Chromosomal translocations can lead to the formation of chimeric genes encoding fusion proteins such as PML/RARα, PLZF/RARα, and AML-1/ETO, which are able to induce and maintain acute myeloid leukemia (AML)." (PMID 21811629, 2011).
acute myeloid leukemia (continued). "A study found that several vital oncogenes in acute myeloid leukemia (AML), such as AML1-ETO, PML/RARa, and PLZF/RARa, induce leukemogenesis by activating c-Myc." (PMID 38611876, 2024). "In line with this, we could show that pharmacological inhibition of 5-LO by CJ-13,610 also affects the aberrant stem cell capacity in a PML/RARα-positive model of AML (acute myeloid leukemia) and a murine cancer stem cell (CSC) model." (PMID 39268466, 2024). "For instance, PML–RARα and FUS–DDIT3 have been considered as the key drivers of acute myeloid leukemia (AML) and mucinous liposarcoma (MLS)." (PMID 37375228, 2023). "Recurrent gene rearrangements are present in 30–40% of acute myeloid leukemia (AML), and well-described driver fusions sometimes suffice to diagnose leukemias (for example, PML::RARA, or RUNX1::RUNX1T1 among others)." (PMID 37699001, 2023). "As proof of principle, we describe a patient with an unclassified myeloproliferative neoplasm harboring a novel PML-SYK fusion, who progressed to acute myeloid leukemia despite chemotherapy and allogeneic stem cell transplant." (PMID 34040147, 2021). "APL is a distinct subtype of acute myeloid leukemia (AML), and 98% of these patients have balanced reciprocal translocations between chromosomes 15 and 17 that result in the fusion of the promyelocytic leukemia (PML) and retinoic acid receptor α (RARα) gene." (PMID 22134377, 2012). "The distribution of RUNX1-RUNXT1, PML-RARA, CBFB-MYH11, BCR-ABL1p210, and KMT2A-MLLT3 in the pediatric population with acute myeloid leukemia (AML) in many countries of Latin America is largely unknown." (PMID 36452349, 2022). "This last designation is in contrast to the WHO, which still requires blast counts of at least 20% for a diagnosis of acute myeloid leukemia (AML) in the absence of certain specific AML-defining genetic abnormalities (e.g., PML::RARA fusion, RUNX1::RUNX1T1 fusion, etc)." (PMID 39941875, 2025). "Specimens included twelve APL specimens at initial diagnosis with PML::RARA fusion by standard-of-care genetic tests and six acute myeloid leukemia specimens without PML::RARA fusion." (PMID 39766302, 2024).
viral infection (98 papers, 2008 to 2025). "Here, we report that HBV core represents a novel player in the rcDNA-to-cccDNA conversion and that SUMO PTM and PML-NBs are host regulators of this pathogenic process to establish a persistent viral infection in human hepatocytes." (PMID 37199632, 2023). "Analysis of PML knockout mice and their derived cell lines (PML−/−) shows that they are more susceptible to viral infections." (PMID 33968942, 2021). "PML NBs are implicated in various processus including stress response, apoptosis, protein degradation, viral infection and IFN response." (PMID 33968942, 2021). "The PML protein has been implicated in diverse cellular processes ranging from tumor suppression to defense against virus infection." (PMID 31416160, 2019). "PML NBs act as a first line of defense against viral infection, specifically by associating with and silencing viral genes." (PMID 30745338, 2019). "Ubiquitin-mediated degradation appears to be the common mechanism accounting for loss of the tumor suppressor promyelocytic leukemia (PML) in virus infection and cancer." (PMID 27058621, 2016). "It has generally been observed that cells with decreased or absent PML have enhanced viral replication and that PML-/- mice are more susceptible to certain viral infections." (PMID 23795346, 2012). "Although total PML loss has been extensively studied both in cell and mouse knockout models, little is known about the roles of isoform‐specific loss with the exception of viral infection and immunity." (PMID 30927552, 2019). "PML NBs have been linked to many viral infections, including cytomegalovirus (CMV) (40, –, 48), herpesviruses, adenoviruses, and papovaviruses (33, –, 35), hepatitis delta virus (49, –, 51), and HBV (52, –, 59), and HBV Cp and polymerase have been reported to interact with PML NBs during infection." (PMID 29669885, 2018). "PML bodies have been previously linked to immunological responses to viral infection." (PMID 28981850, 2017). "Interestingly, PML (promyelocytic leukemia protein), involved in chromatin metabolism and DNA repair, has been associated with response to viral infection." (PMID 24812617, 2014). "Other viral infections have also been association with the disruption of PML-NBs." (PMID 23526763, 2013). "However, speculation such as disruption of PML NBs upon viral infection is linked to activation rather than inhibition of innate immunity is subject to further studies in other virus infection scenario." (PMID 34513832, 2021). "Thus, elucidating the mechanisms implicated in virus-dependent PML degradation could help to provide strategies for developing antiviral therapies that prevent viral infections." (PMID 23734343, 2013). "Loss of PML may increase the vulnerability to viral infection." (PMID 22947142, 2012). "PML gene functions as a universal sensor of cellular stress, including viral infection, oxidative stress, and DNA damage, capable of initiating diverse protective cellular responses." (PMID 41312366, 2025). "HIRA has previously been shown to localize to PML-NBs during viral infection, cellular senescence or after interferon treatment and here we show that this localization can also be promoted by keratinocyte differentiation." (PMID 41019635, 2025). "Daxx is constitutively associated with PML-NBs, while the histone H3.3 chaperone HIRA only associates with PML-NBs in response to cellular senescence, interferon (IFN) stimulation, and viral infection." (PMID 40568077, 2025). "An early cellular response to viral infections, including HCMV ones, has been associated, by numerous studies, with the recruitment of heterochromatin protein 1 (HP1) by PML-NB nuclear bodies, acting as a first barrier to the initial stages of viral infection." (PMID 41373712, 2025). "The histone chaperone, HIRA localizes to PML-NBs in response to viral infection or transfection with plasmid DNA, both of which induce secretion of IFNs." (PMID 40568077, 2025).